ENSG00000276494
Gene: Miscellaneous RNA gene on chromosome 11 (2,674,625 to 2,674,740, forward strand). Ensembl gene ENSG00000276494.
Gene Ontology:
Biological process: heterochromatin formation
Cellular component: nucleolus